ZBTB38 (zinc finger and BTB domain containing 38)
Diseases named in the same sentence as ZBTB38 in open-access papers (continued):
Sharing a sentence is not in itself a finding about the gene and the disease.
glioma (1 paper, 2022). A benign or malignant brain and spinal cord tumor that arises from glial cells (astrocytes, oligodendrocytes, ependymal cells).
hyperplasia of prostate (1 paper, 2023). "Association of ZBTB38, zinc finger and BTB domain containing 38, with benign hyperplasia of prostate (BHP) is a compelling finding given that both gestational duration and BHP are affected by changes in estrogen and androgen levels." (PMID 37871108, 2023).
leukemia (1 paper, 2018). A malignant (clonal) hematologic disorder, involving hematopoietic stem cells and characterized by the presence of primitive or atypical myeloid or lymphoid cells in the bone marrow and the blood. "We investigated the kinetics of cell proliferation when ZBTB38 depletion is combined with decitabine or azacytidine exposure in leukemia cells." (PMID 30310057, 2018). "We thus concluded that the transient depletion of ZBTB38 at the time of decitabine exposure negatively impact leukemia cell proliferation even after the return to the normal culture conditions." (PMID 30310057, 2018). "The depletion of ZBTB38 by RNA interference enhances the toxicity of DNMTi in cell lines from leukemia and from various solid tumor types." (PMID 30310057, 2018). "In three additional human cancer types (U2OS, HepG2, and HCT116) and two leukemia cell types (THP-1 and MOLM-14) we also observed that exposure to 5-azacytidine causes the down-regulation of ZBTB38 protein abundance without altering the mRNA level." (PMID 30310057, 2018). "In addition, we demonstrated that the depletion of ZBTB38, or its regulator deubiquitinase USP9X, enhances the cytotoxicity of 5-azacytidine derivatives in different cancer and leukemia cells, which was concomitant with the enhanced expression of CDKN1C mRNA." (PMID 30310057, 2018).
metastatic prostate carcinoma (1 paper, 2020). A carcinoma that arises from the prostate gland and has spread to other anatomic sites. "We observed that ZBTB38 is rarely mutated or rearranged in localised and metastatic prostate cancer." (PMID 32365491, 2020). "In the four cohorts reporting gene expression data in metastatic prostate cancer, we observed a significant decrease of ZBTB38 expression levels in metastatic prostate cancer compared to normal/benign prostate tissues, as well as localised prostate cancer." (PMID 32365491, 2020). "We show that ZBTB38 expression is decreased in localised prostate cancer, and further in metastatic prostate cancer." (PMID 32365491, 2020). "However, we observed that ZBTB38 has significantly lower level of expression in localised prostate cancer compare to benign tissues and the difference is extended in metastatic prostate cancer, whether ZBTB38 expression was monitored by micro-array or RNA-sequencing technology." (PMID 32365491, 2020). "Monitoring ZBTB38 expression level in tumours might thus be useful, in combination with other genetic alterations (i.e., SPOP/SPOPL), to target metastatic prostate cancer with doxorubicin-based therapies." (PMID 32365491, 2020).
metastatic tumours (1 paper, 2020). "Our analysis revealed that ZBTB38 expression correlates with overall genomic instability in localised but not in metastatic tumours." (PMID 32365491, 2020).
neuroma (1 paper, 2019). A tumor that grows from a nerve or is composed of nerve cells and nerve fibers. "However, in our study, the statistical analysis of the prognosis of the LGG patients exhibited a negative correlation with the expression changes of ZBTB38, indicating a significant concern regarding the study of the effects of ZBTB38 expression changes on the occurrence and development of neuroma." (PMID 30697495, 2019).
neuronal tumor (1 paper, 2019). Neuronal brain tumors are an uncommon group of central nervous system tumors that arise from cells with neuronal differentiation. "However, in the prognosis of these 20 tumors, we only uncover here that low expression of ZBTB38 was associated with improved the prognosis of the brain lower grade glioma (LGG) patients, suggesting that these changes are closely related to neuronal tumors." (PMID 30697495, 2019).
ovarian carcinoma (1 paper, 2022). A malignant neoplasm originating from the surface ovarian epithelium. "Indeed, BATF3, IRF5 and ZBTB38 also contributed in evaluation of the response to chemotherapy of breast and ovarian cancer patients." (PMID 35410350, 2022).
prion disease (1 paper, 2014). A transmissible disease that is caused by a protein that is able to induce abnormal folding of normal cellular proteins, leading to characteristic spongiform brain changes, which are associated with neuronal loss without an inflammatory response. "STMN2 was identified as a prion disease susceptibility factor in vCJD, and ZBTB38 and SORCS1 were identified in a meta-analysis of vCJD, sCJD and kuru resistance GWAS data." (PMID 24833721, 2014).
prostate tumours (1 paper, 2020). "Our data show a significant association between low ZBTB38 expression levels and more aggressive and recurrent prostate tumours." (PMID 32365491, 2020). "Altogether, these results suggest that monitoring ZBTB38 mRNA expression level may help identify localised prostate tumours with aggressive features, such as genomic instability and invasive properties." (PMID 32365491, 2020). "ZBTB38 mRNA expression, in combination with other genetic alterations (i.e., SPOP/SPOPL), might thus be useful to identify localised prostate tumours that will exhibit more aggressive behaviour and target metastasis with doxorubicin-based therapies." (PMID 32365491, 2020).
rheumatoid arthritis (1 paper, 2022). A chronic, systemic autoimmune disorder characterized by inflammation in the synovial membranes and articular surfaces. "Zbtb38 is ubiquitously expressed in tissues, and its expression is associated with height, cancers, neurodegenerative diseases, rheumatoid arthritis." (PMID 35297517, 2022).
schizophrenia (1 paper, 2019). A major psychotic disorder characterized by abnormalities in the perception or expression of reality. "Of these, Plscr4, Armc8, Zbtb38, Rbp1, Zic1, and Trpc1 have been linked to schizophrenia or schizophrenia-related disorders in previous studies." (PMID 31920576, 2019).
Stroke (1 paper, 2020). Sudden impairment of blood flow to a part of the brain due to occlusion or rupture of an artery to the brain. "Neuronal insult, such as injury, stroke, or cancer may be necessary to identify processes regulated by ZBTB38." (PMID 32956421, 2020).
cancer (15 papers, 2017 to 2026). A tumor composed of atypical neoplastic, often pleomorphic cells that invade other tissues. "It was also showed that down-regulation of ZBTB38 potentiates the efficacy of anti-cancer DNA demethylating agent 5-azacytidine while causing heightened levels of reactive oxygen species (ROS)." (PMID 32365491, 2020). "Low expression levels of ZBTB38 are also associated with higher cancer recurrence in patients with intermediate risk, i.e., Gleason score = 7, in the TCGA cohort." (PMID 32365491, 2020). "Nevertheless, our results indicate that ZBTB38 loss of expression correlates with clinico-pathological features predictive of cancer aggressiveness and advanced stage of the disease." (PMID 32365491, 2020). "In conclusion, 5-azacytidine causes ZBTB38 down-regulation in different cancer cell types, mainly at the protein level and most likely in a proteasome-dependent manner." (PMID 30310057, 2018). "The low expression of ZBTB38 is associated with increased genomic instability in localised tumours, which may favour cancer progression." (PMID 32365491, 2020). "One can thus speculate that low levels of ZBTB38 in tumours might be associated with higher levels of ROS causing genomic instability that further fuel cancer progression." (PMID 32365491, 2020). "Treatment of a variety of cancer cells with DNA methyltransferase inhibitors (DNMTi) results in downregulation of ZBTB38 protein expression via proteasomal degradation due to upregulation RBBP6." (PMID 35178492, 2022). "The expression of ZBTB38 is significantly lower in cancer tissues compared with benign prostatic epithelia." (PMID 34697293, 2021). "We identified a recurrent up-regulation of CDKN1C expression at the mRNA level in different cancer cell types silenced for ZBTB38 or its deubiquitinase USP9X." (PMID 30310057, 2018). "Altogether, our results demonstrate that depletion of ZBTB38 enhances the cytotoxicity of several DNMT inhibitors in various cancer cells." (PMID 30310057, 2018). "Further studies will be required to clarify the direct and indirect regulation of CDKN1C expression by ZBTB38 in normal and cancer cells." (PMID 30310057, 2018). "Treatments with 5-azacytidine, or its derivatives decitabine and zebularine, lead to down-regulation of ZBTB38 protein expression in cancer cells, in parallel with cellular damage." (PMID 30310057, 2018). "The evaluation of ZBTB38 in cancer has been limited, though several studies have correlated ZBTB38 transcriptional activities with disease relevant pathways, such as apoptosis, proliferation, and differentiation." (PMID 30301273, 2018). "Here, we demonstrate that transient inhibition of ZBTB38 expression by siRNAs enhances the toxicity of 5-azacytidine, and its derivatives, in different cancer types." (PMID 30310057, 2018). "Moreover, down‐regulation of ZBTB38 expression potentiates the toxicity of anti‐tumour reagents in cancer cells." (PMID 35297517, 2022). "The model we created and based on the expression of 3 genes, BATF3, IRF5, ZBTB38, could help in the prediction of the reaction and prognosis of cancer patients given platinum-based, especially cisplatin-including chemotherapies." (PMID 35410350, 2022). "A couple of studies have addressed the function of ZBTB38 in cancer." (PMID 32365491, 2020). "It is thus likely that low expression of ZBTB38 mRNA in localised tumours might contribute to cancer aggressiveness and/or progression." (PMID 32365491, 2020). "Our findings suggest that measuring ZBTB38 mRNA levels in tumours may help better anticipate chromosomal instability in localised tumours, cancer aggressiveness and doxorubicin efficacy." (PMID 32365491, 2020). "Among ZBTB genes, the expression changes of ZBTB38 gene are closely related to the occurrence of 20 kinds of cancers, and different tumors exhibit significant differential expression changes, especially the remarkably down-regulated expressions of UCEC and CESC." (PMID 30697495, 2019).
cancer (continued). "We tested whether ZBTB38 inactivation would modulate the cytotoxicity of 5-azacytidine in cancer cells." (PMID 30310057, 2018). "ZBTB38 regulates gene expression and reports show that altering its abundance affects cell differentiation, cell homeostasis and cell survival, and may be involved in the initiation and/or progression of cancer." (PMID 32365491, 2020). "We then directly investigated the relationship between RBBP6, USP9X, ZBTB38, and CDKN1C expression and the clinical response to azacytidine in cancer patients." (PMID 30310057, 2018). "Third, ZBTB38 paralogs, ZBTB4 and ZBTB33, regulate the expression of CDKN1 family genes in cancer cells." (PMID 30310057, 2018). "Its depletion can either promote, reduce, or not affect cell proliferation according to cell type; thus, ZBTB38 functions as a potential oncogene or tumor suppressor in cancer." (PMID 38302914, 2024). "Collectively, our results suggest that the ZBTB38 protein is a target of DNMTi and that its depletion potentiates the toxicity of DNMT inhibitors in cancer cells, providing new opportunities to enhance the response to DNMT inhibitor therapies in patients with MDS and other cancers." (PMID 30310057, 2018).
tumor (13 papers, 2012 to 2026). "Our analyses revealed that low expression levels of ZBTB38 in tumours associates, in several independent cohorts, with higher PSA levels at diagnosis and pathological grade." (PMID 32365491, 2020). "On the contrary, tumours with high levels of ZBTB38 are associated with recurrent fusions of ETS transcription factor genes and a less rearranged genome." (PMID 32365491, 2020). "It is of note that tumor size was also related to the genome alteration pattern, and was associated with amplification and overexpression of Zbtb38 located on chromosome 8." (PMID 22952676, 2012). "Notably, we show that loss of ZBTB38 expression may constitute a tumour subclass with increased genomic instability." (PMID 32365491, 2020). "Therefore, in the present study, a high-throughput transcriptome sequencing approach was adopted to investigate the transcriptome profiles of NB cells in which the expression of ZBTB38 gene was down-regulated, thus revealing the potential biomarkers associated with anti-tumor therapies for NB." (PMID 30697495, 2019). "Analysis of human tumor datasets reveals a strong positive correlation between ZBTB38 and XIAP expression, with elevated ZBTB38 levels associated with high-grade malignancies." (PMID 41842907, 2026). "Taken together, our findings in this study uncovered the tumor-suppressive roles of ZBTB38 to suppress cell proliferation and migration by upregulating DKK1 expression." (PMID 34697293, 2021). "We also observed that disease-free survival was significantly shorter for white patients with lower ZBTB38 expression in tumours (p = 0.006), and a similar tendency was observed for black/African American patients." (PMID 32365491, 2020). "Our analysis identified 216 genes differentially expressed between tumours expressing low and high levels of ZBTB38 in at least three cohorts; and five genes differentially expressed in the four cohorts." (PMID 32365491, 2020). "We thus investigated the relationship between ZBTB38 expression and genomic parameters in metastatic tumours from three different datasets." (PMID 32365491, 2020). "A comparison of tumours with high and low expression of ZBTB38 reveals a signature of 216 genes differentially expressed." (PMID 32365491, 2020). "The present meeting provides evidence to molecular mechanism of ZBTB38 modulating NB development and targeted anti-tumor therapies." (PMID 30697495, 2019). "We identified DKK1 as the direct downstream of ZBTB38, which could mediate the tumor-suppressing function." (PMID 34697293, 2021). "Finally, results of the xenograft tumor model using DU145 cells also revealed that upregulation of ZBTB38 expression induced the growth inhibition of tumor in vivo." (PMID 34697293, 2021). "It would thus be interesting to investigate whether a combination between expression levels of ZBTB4, ZBTB33/KAISO and ZBTB38 may help better categorised tumours with different molecular and clinical behaviour." (PMID 32365491, 2020). "Consistently, low expression of ZBTB38 is correlated with the same integrative Cluster 1 (p < 0.00001), DNA methylation cluster 2 (p < 0.00001) and mRNA cluster 1 (p < 0.00001) as SPOP mutation molecular subgroup of tumours." (PMID 32365491, 2020). "Two DEGs (PIK3C2A and RB1CC1) that closely related to autophagy initiation were significantly inhibited, suggesting that ZBTB38 downregulation also blocked autophagy, an important mechanism that protects the cells from programmed cell death, thus accelerating apoptosis of tumor cells." (PMID 30697495, 2019). "Another potential candidate tumor promotion susceptibility gene, Zbtb38 (zinc finger and BTB domain containing 38), maps to a region of nonequivalency within the Psl1.1b locus and has an amino acid variant between C57BL/6 and DBA/2." (PMID 24700353, 2014).
tumor (continued). "Importantly, we found that PRKDC could inhibit the tumor-suppressive function of ZBTB38, as PRKDC knockdown resulted in the increase of DKK1 expression and enhanced the tumor-suppressive function of ZBTB38." (PMID 34697293, 2021). "ZBTB38 expression levels may help discriminate aggressive-prone localised prostate tumours with a greater likelihood of tumour spread to lymph node and worst outcome, from tumours who can benefit only from observation." (PMID 32365491, 2020). "In addition, ZBTB38 expression is further lower in metastatic samples compare to localised tumours." (PMID 32365491, 2020). "Besides confirming previous results, our results also showed the binding affinity of ZBTB38 using ChIP-seq analysis and identified DKK1 as the direct downstream of ZBTB38.expression in mediating its tumor-suppressive role." (PMID 34697293, 2021). "We observed that low expression of ZBTB38 correlates with shorter disease-free survival in patients with Gleason 4 + 3 tumours (p < 0.001) while there is no clear correlation in patient with Gleason 3 + 4 tumours." (PMID 32365491, 2020).
genetic diseases (1 paper, 2024). "We identified four high-impact variants in four candidate novel genes (ZBTB38, AQR, APBA1, and TXLNA) not implicated before in NDD or genetic diseases in four probands/families." (PMID 38300321, 2024).
hematologic cancer (1 paper, 2018). "Altogether our work suggests that inhibition (or inactivation) of ZBTB38 or USP9X expression may be a new strategy to enhance the clinical efficacy of DNMTi in hematological and non-hematological cancers." (PMID 30310057, 2018).
ZBTB38 also shares sentences with these, for which no sentence is quoted: alcoholic cirrhosis (1 paper); alcoholism (1); autoimmune disease (1); cervical squamous cell carcinoma (1); diabetes (1); endocervical adenocarcinoma (1); hyperopia (1); liver disease (1); metabolic disease (1); neurodegenerative disease (1); non-small cell lung carcinoma (1); psychiatric disorder (1); sarcopenia (1); spinal cord injury (1); Type 2 Diabetes (1); uterine corpus endometrial carcinoma (1); viral hepatitis (1).